PINK1 (PTEN induced kinase 1)
Diseases named in the same sentence as PINK1 in open-access papers (continued):
Sharing a sentence is not in itself a finding about the gene and the disease.
colorectal cancer (continued). "Differential transcriptional patterns of BECN1, PINK1, and LAMP2 were observed across colorectal cancer stages, suggesting that distinct autophagy pathways may be differentially regulated in inflammation-associated and sporadic colorectal tumorigenesis." (PMID 41614861, 2025). "The transcriptional activity of genes involved in the autophagy process (LAMP-2, BECN1, PINK1, FOXO1) in colorectal cancer biopsies in four clinical stages of adenocarcinoma (CSI, CSII, CSIII, CSIV) was compared with that of controls (colon samples assessed as histopathologically normal)." (PMID 36830954, 2023). "To explore whether the interaction of PINK1 and PTEN is universal in tumor cells, we repeated co-IP analysis in the colorectal cancer cell line SW480 and confirmed the extensive existence of the interactions between PINK1 and PTEN." (PMID 37940999, 2023). "Heterozygous PINK1 mutations in PD and MUTYH mutations in colorectal cancer do not confer an increased risk of PD or cancer, respectively." (PMID 33448283, 2021). "High PINK1 expression promotes proliferation and chemoresistance in non-small cell lung cancer, and upregulated PTGS2 expression is associated with increased risk of colorectal cancer and increased cell migration ability." (PMID 39951474, 2025). "Moreover, siRNA screening reveals that several genes, such as PTEN-induced kinase 1 (PINK1) and Cysteine rich motor neuron 1 (CRIM1), may play drug-resistance roles in colorectal cancer cells when exposed to MEK inhibitor trametinib." (PMID 34830933, 2021).
acute kidney injury (28 papers, 2019 to 2026). Sudden and sustained deterioration of the kidney function characterized by decreased glomerular filtration rate, increased serum creatinine or oliguria. "It presented macrophage migration inhibitory factor (MIF) as a suppressor of mitophagy through the disruption of PINK1–Parkin protein interactions in sepsis-associated acute kidney injury, thereby promoting renal damage." (PMID 40497970, 2025). "At the same time, PINK1 and Parkin mediated mitophagy also plays a protective role in renal ischemia–reperfusion injury or acute kidney injury caused by sepsis." (PMID 39267971, 2024). "Together, these results suggested PINK1 deficiency ameliorated cisplatin-induced acute kidney injury in rats, possibly via inhibiting DRP1-mediated mitochondrial fission and excessive mitophagy." (PMID 31607953, 2019). "Here we used PINK1 knockout (KO) rats and found that PINK1 deficiency ameliorated cisplatin-induced acute kidney injury." (PMID 31607953, 2019). "In summary, our results showed that renal mitophagy was activated in cisplatin treated rats and PINK1 deficiency ameliorated cisplatin-induced acute kidney injury accompanied by a decrease of mitophagy." (PMID 31607953, 2019). "Existing research has demonstrated that inhibiting PINK1 can mitigate oxidative stress and alleviate acute kidney injury, further justifying our focus on PINK1." (PMID 39242558, 2024). "In both in vivo and in vitro models, berberine enhanced mitophagy by increasing the LC3-II/LC3-I ratio and PINK1/Parkin protein levels and decreasing P62 protein levels, thereby protecting against acute kidney injury in mice." (PMID 37168854, 2023). "The present study was designed to investigate BNIP3-mediated and PINK1-PARK2-mediated mitophagy and its regulation of ferroptosis in a cisplatin-induced acute kidney injury model using Pink1, Park2 and Bnip3 knockout mice." (PMID 36923942, 2023). "The PINK1/PARK2/OPTN (optineurin) pathway of mitophagy is activated for protection in septic acute kidney injury." (PMID 36187470, 2022). "Our previous research demonstrated that the expression of Parkin and Pink1 was increased after Cisp treatment, and the downregulation of mitophagy exacerbated Cisp-induced acute kidney injury." (PMID 33714196, 2021). "Consistently, Dex can upregulate the expression of autophagy and mitophagy related proteins, such as Beclin-1, LC3 II and PINK1, and thus enhances autophagy, resulting in the removal of damaged mitochondria in lipopolysaccharide (LPS)-induced acute kidney injury." (PMID 34772407, 2021). "In present study, PINK1 deficiency remarkably restrained cisplatin-induced DRP1 up-regulation, indicating the regulation of DRP1 by PINK1/Parkin pathway might play a key role in cisplatin-induced acute kidney injury." (PMID 31607953, 2019). "Besides, there is evidence that PINK1-parkin pathway of mitophagy protects against contrast-induced acute kidney injury via decreasing mitochondrial ROS and NLRP3 inflammasome activation." (PMID 31607953, 2019). "In addition, existing literature has shown that inhibition of PINK1 could suppress oxidative stress and alleviate acute kidney injury." (PMID 39242558, 2024). "In diabetic nephropathy or acute kidney injury (AKI), the expression of the aging markers p16 and SA-β-gal in renal tubule cells was increased, which was accompanied by a decrease in PINK1, Parkin and LC3 expression levels." (PMID 37397494, 2023). "Importantly, Bnip3 knockout, Pink1 knockout and Park2 knockout mice showed more severe kidney injury than WT mice, suggesting the important roles of mitophagy and mitochondrial quality control in cisplatin-induced acute kidney injury." (PMID 36923942, 2023). "A study confirmed that Mitophagy, dependent on PINK1 and Parkin, was activated in renal proximal tubular cells in acute kidney injury (AKI)." (PMID 34526554, 2021).
acute kidney injury (continued). "Therefore, it is not surprising that both apoptosis and mitophagy/autophagy were attenuated in PINK1 KO rats in present study and this may also indicate excessive mitophagy/autophagy during cisplatin-induced acute kidney injury." (PMID 31607953, 2019). "In a contrast-induced acute kidney injury (CI-AKI), the activation of PINK1-Parkin-mediated mitophagy ameliorates tissue damage and suppress apoptosis in renal tubular epithelial cells (RTECs) through the inhibition of mitochondrial ROS and NLRP3 inflammasome activation." (PMID 32630319, 2020). "In contrast-induced acute kidney injury (CI-AKI), the PINK1/Parkin pathway also protects RTECs from apoptosis by reducing oxidative stress and inhibiting nucleotide-binding oligomerization domain-like pyrin domain containing protein 3 (NLRP3) inflammasome production." (PMID 40225869, 2025). "Further, the present study used Pink1 knockout, Park2 knockout and Bnip3 knockout mice to confirm the protective role of both PINK1-PARK2-mediated and BNIP3-mediated mitophagy in cisplatin-induced acute kidney injury." (PMID 36923942, 2023). "From our previous study findings, in contrast-induced acute kidney injury (CI-AKI), PINK1/PARK2-mediated mitophagy downregulated ROS-mediated DNA oxidative damage and mitochondrial ROS generation in renal tubular epithelial cells to maintain the redox balance of tubular epithelial cells." (PMID 36755884, 2022). "Therefore, the reduced apoptotic level in PINK1 KO rats may partly due to the inhibition of DRP1 and mitochondrial fission during cisplatin-induced acute kidney injury." (PMID 31607953, 2019). "However, the aggravation of cisplatin-induced acute kidney injury in Bnip3/Pink1/Park2 knockout mice was not attributed to only the pharmacological action of cisplatin, which indicated that mitophagy may have an effect on renal volume." (PMID 36923942, 2023).
cardiac hypertrophy (28 papers, 2016 to 2025). "Consistently, in our earlier research, we demonstrated that PINK1 deficiency exacerbated angiotensin II‐induced cardiac hypertrophy and impaired cardiomyocyte mitochondrial function, which was associated with HFrEF exacerbation." (PMID 39763059, 2025). "It has also been reported that mice deficient in Pink1 develop early left ventricular dysfunction and pathological cardiac hypertrophy." (PMID 35845350, 2022). "To further elucidate the underlying mechanism of Samm50 in the regulation of myocardial hypertrophy, we first detected the expression of Pink1 and Parkin in response to Ang II stimulation." (PMID 34631840, 2021). "Moreover, PINK1 deficiency in mice exacerbated angiotensin II‐induced cardiac hypertrophy and compromised cardiomyocyte mitochondrial function." (PMID 39763059, 2025). "Moreover, it has been proved that loss of PINK1 lead to cardiac hypertrophy and mitochondrial dysfunction in mice at 2 months of age." (PMID 35534453, 2022). "Also, the depletion of Pink1, a key mediator of mitophagy, caused left ventricular dysfunction and pathological cardiac hypertrophy in mice by 2 months of age." (PMID 34603595, 2021). "PINK1 deficiency disrupts mitophagy mediated by PINK1, leading to the inactivation of mitophagy, a loss of myocardial tissue movement, and the development of cardiac hypertrophy." (PMID 34751247, 2021). "However, the protective role of Samm50 deficiency against cardiac hypertrophy was abolished by inhibiting mitophagy through Vps34 inhibitor or Pink1 knockdown." (PMID 34631840, 2021). "Moreover, PINK1 knockdown was closely linked to the occurrence of cardiac hypertrophy." (PMID 37106782, 2023). "Our data showed that TAC mice developed cardiac hypertrophy and HF, and these changes coincided with decreased PINK1/Parkin-mediated mitophagy levels." (PMID 40015131, 2025). "Previous studies have shown that PINK1 is a vital protein involved in the mitophagy process, and its knockdown is closely related to the occurrence of cardiac hypertrophy." (PMID 37106782, 2023). "Cardiac-specific overexpression of PINK1 improved cardiac function, attenuated pressure overload-induced cardiac hypertrophy and fibrosis, and facilitated myocardial mitophagy in TAC mice." (PMID 37106782, 2023). "The importance of PINK1 pathway in the heart was also shown by deletion of PINK1 that induces baseline cardiac phenotype with left ventricular (LV) dysfunction, cardiac hypertrophy, oxidative stress and impaired mitochondrial function." (PMID 35053316, 2022). "Mice with Parkin or Pink1 depletion exhibit enhanced cardiac hypertrophy and contractile dysfunction in response to pressure overload." (PMID 35845350, 2022). "PINK1 was downregulated in the hearts of end-stage HF patients, and PINK1-/- mice also showed age-dependent cardiac hypertrophy and ultimately developed HF." (PMID 35844503, 2022). "Lysocardiolipin acyltransferase 1 (ALCAT1) deletion upregulates PINK1 and mitigates oxidative stress, insulin resistance, and mitochondrial dysfunction via activation of PINK1-mediated mitophagy and alleviating cardiac hypertrophy." (PMID 35096821, 2021). "In conclusion, our present study shows Samm50 aggravates cardiac hypertrophy by regulating the Pink1-Parkin signaling and further clarifies the relationship between mitophagy and cardiac hypertrophy." (PMID 34631840, 2021). "Collectively, we first discovered that Samm50-mediated mitophagy in cardiac hypertrophy was largely dependent on Pink1-Parkin signaling." (PMID 34631840, 2021). "PINK1 knockout mice develop cardiac hypertrophy and left ventricular dysfunction by 2 months of age, which was associated with increased oxidative stress and mitochondrial dysfunction." (PMID 33101051, 2020). "Recently, studies in pressure overload-induced cardiac hypertrophy and HF models highlight the role of AMPKα2 in the regulation of PINK1–PARKIN-dependent mitophagy." (PMID 32679729, 2020).
cardiac hypertrophy (continued). "In response to biomechanical stress, the Pink1 knockout mice developed a further exaggeration in the degree of cardiac hypertrophy." (PMID 29267372, 2017). "A deficiency of the PINK1 protein induced inflammation in mouse myocardium and promoted cardiac hypertrophy, whereas the overexpression of the cardiac-specific PINK1 protein inhibited cGAS-STING signaling and prevented cardiac hypertrophy." (PMID 41241888, 2025). "More importantly, we constructed myocardial-specific overexpression in mice and found that cardiac-specific overexpression of PINK1 improved cardiac function, attenuated pressure overload-induced cardiac hypertrophy and fibrosis and facilitated myocardial mitophagy in TAC mice." (PMID 37106782, 2023). "In a previous study, PINK1 knock-out mice exhibited abnormal cardiac mitochondrial function and elevated oxidative stress, with early left ventricular dysfunction and pathological cardiac hypertrophy." (PMID 37492732, 2023). "In addition, PINK1 contributes to the maintenance of cardiac function because PINK1 knockout mice develop LV dysfunction and pathological cardiac hypertrophy with impaired mitochondrial function." (PMID 36758801, 2023). "Therefore, PINK1 was involved in mitophagy induction in response to TAC-induced cardiac hypertrophy." (PMID 37106782, 2023). "In addition, PINK1-KO mice developed left ventricular dysfunction and cardiac hypertrophy, during earlier stages of life, while PINK1 expression was significantly downregulated in the left ventricles of patients with end-stage heart failure." (PMID 35821839, 2022). "To evaluate whether Pink1 is required for Samm50-mediated cardiac hypertrophy, we interfered with the expression of Pink1 in the absence of Samm50." (PMID 34631840, 2021). "Agreed with the previous study, our results showed that Samm50 could directly interact with Pink1 in the cardiac hypertrophy model." (PMID 34631840, 2021). "Moreover, the ablation of PINK1 in mice induces cardiac hypertrophy at two months of age, and PINK1 knockout aggravates the infarct size after ischemia/reperfusion (I/R) injury." (PMID 34603595, 2021). "Although Samm50 is a key regulatory factor of Pink1 and might affect mitophagy, whether it regulate the Pink1-Parkin pathway and involve in cardiac hypertrophy remains poorly understood." (PMID 34631840, 2021). "PINK1 knockout mice show spontaneous age-dependent cardiac hypertrophy." (PMID 34751247, 2021). "Indeed, a study using pressure overload-induced cardiac hypertrophy and HF models highlighted the role of AMPKα2 in the regulation of PINK1–PARKIN-dependent mitophagy." (PMID 32679729, 2020). "PINK1/Parkin pathway was proved to participate in pathological cardiac hypertrophy and HF." (PMID 33101051, 2020). "Our findings suggested that PINK1/Parkin/Ubiquitin mechanism may be involved in berberine mediated cardioprotective effects on TAC-induced adverse cardiac hypertrophy, and even on chronic HF." (PMID 33101051, 2020). "PTEN-inducible kinase 1 (PINK1) is downregulated in patients with end-stage heart failure, and PINK1(−/−) mice exhibit elevated oxidative stress, impaired mitochondrial function, increased fibrosis, ventricular dysfunction, and cardiac hypertrophy." (PMID 27747225, 2016). "Several studies have shown that the downregulation of PINK1 and BNIP3/NIX in a genetic intervention model induces pathological cardiac hypertrophy and cardiomegaly." (PMID 39335620, 2024). "We studied the function of PINK1 in mitophagy in isoproterenol (Iso)-induced cardiomyocyte injury and transverse aortic constriction (TAC)-induced myocardial hypertrophy." (PMID 37106782, 2023). "We found that overexpression of PINK1 could increase mitophagy and alleviate Iso-induced cardiomyocyte injury and TAC-induced myocardial hypertrophy." (PMID 37106782, 2023).
myocardial infarction (26 papers, 2013 to 2025). Gross necrosis of the myocardium, as a result of interruption of the blood supply to the area, as in coronary thrombosis. "For instance, PINK1 deficient-mice had enhanced oxidative stress and higher degrees of cardiomyocyte apoptosis Kubli and coworkers showed that mice with global deletion of Parkin were more sensitive to myocardial infarction, which was mainly attributed to the impaired mitophagy in cardiomyocytes." (PMID 27119505, 2016). "This mitochondrial protein appears to be required for endogenous protection against SIRI, as its genetic ablation resulted in an enhanced susceptibility to myocardial infarction, a response which was graded according to whether one or both PINK1 alleles were knocked-out." (PMID 23638067, 2013). "It was shown to improve cardiac function in mice post-myocardial infarction by enhancing mitophagy through the Pink1/Parkin signaling pathway, and to improve cardiac function in STZ-induced diabetic mice by promoting AGTR1/TRPV1-mediated autophagy." (PMID 41178953, 2025). "Knockdown of ZIP7 reduces mitochondrial ROS generation and myocardial infarction by increasing Zn2+ in mitochondria, leading to mitochondrial depolarization and the accumulation of PINK1 and Parkin." (PMID 39737905, 2024). "Promotes cardioprotection, decreasing myocardial infarction size, autophagy, and cell death via Pink1/FAM65B axis." (PMID 36768449, 2023). "In vivo myocardial infarction elicits increases in mitochondrial PINK1, Parkin, and ubiquitinated mitochondrial proteins." (PMID 35760846, 2022). "For instance, PINK1/Parkin-mediated mitophagy is activated during pressure-overload, following myocardial infarction (MI), and in I/R." (PMID 32528313, 2020). "In support of our findings, another research group has recently reported that in myocardial infarction, cardiac RhoA signaling plays a role in mitochondrial quality control by regulating the function and expression of Parkin and PINK1, a protein kinase that phosphorylates and activates Parkin." (PMID 36758801, 2023). "Similarly, Linggui Zhugan decoction delays ventricular remodeling in rats with chronic heart failure after myocardial infarction via the Wnt/β-catenin signaling pathway, and Nuanxinkang prevents chronic heart failure induced by myocardial infarction by enhancing PINK1/Parkin-mediated mitophagy." (PMID 40860357, 2025). "Given that myocardial infarction is accompanied by metabolic stress and AMPK activation, it can be inferred that AMPK activation leads to PINK1-Parkin mitophagy, suggesting that mitophagy decelerates the progression of necrotic death in cardiomyocytes." (PMID 39737905, 2024). "In genetic terms, the causality found may be due to alterations in Human Leukocyte Antigen (HLA), CD40, and PINK1/Parkin genes in patients with MS and PD, which modulate the body’s immune-inflammatory response and mitochondrial autophagy, thereby influencing the occurrence of myocardial infarction." (PMID 38850523, 2024). "Zhou and his colleagues found that Pink1 acted as a downstream target of the circRNA ACR to mediate autophagy and myocardial infarction." (PMID 35370737, 2022). "To confirm that PINK1 is not required for recruitment of Parkin to mitochondria in vivo, we subjected WT and PINK1-/- mice to myocardial infarction (MI)." (PMID 26110811, 2015). "Using PINK1-deficient (PINK1-/-) mice, we found that Parkin is recruited to damaged cardiac mitochondria in hearts after treatment with the mitochondrial uncoupler FCCP or after a myocardial infarction even in the absence of PINK1." (PMID 26110811, 2015).